IL33 (interleukin 33)
Diseases named in the same sentence as IL33 in open-access papers (continued):
Sharing a sentence is not in itself a finding about the gene and the disease.
tumor (continued). "Moving forward, the key challenge will be determining whether the same TLS-inducing pathway exists in humans and whether clinical trials can validate the efficacy of an IL-33-based therapy in boosting anti-tumor immunity and improving patient outcomes in PDAC." (PMID 40414898, 2025). "Intra-tumoral IL-33 suppression may compromise local immune surveillance, while systemic IL-33 could represent a compensatory response to tumour progression, potentially influenced by host genetics such as IL-33 SNPs (e.g., rs1929992)." (PMID 40607441, 2025). "IL-33 recruits immune cells that secrete molecules impacting tumor phenotype, including macrophages, mast cells, MDSCs, Tregs, and neutrophils, fostering a tumor-promoting environment and a self-sustaining pro-inflammatory loop." (PMID 39925809, 2025). "This reduction of intra-tumoral IL-33 may impair anti-tumour immune surveillance by weakening the Th1 response, thereby promoting tumour development." (PMID 40607441, 2025). "In addition, IL-33 can affect the infiltration of various immune cells into the TME to affect the tumor process." (PMID 39925809, 2025). "In addition to its regulatory role in proliferation regulation, IL-33 plays an important role in the control of tumor local invasion, migration, and metastasis." (PMID 39925809, 2025). "In vivo, DAC increased the expression of ST2 and IL-33 at the tumor site, suggesting it may enhance endogenous IL-33 production." (PMID 40317004, 2025). "Glioma-derived TPCs express high IL-33, attracting MDSCs to the tumor site." (PMID 40784879, 2025). "Moreover, the combined DAC/IL-33 treatment was the most efficient in promoting immune recruitment (i.e., T cells and eosinophils) at the tumor site and induced the up-regulation of PD-1 resulting in better therapeutic response to PD-1 blockade in vivo." (PMID 40317004, 2025). "Intra-tumoral IL-33 expression is significantly reduced in PCa tissues and correlates with aggressive disease features such as higher Gleason scores and lymphatic metastasis, suggesting an inherent anti-tumour function." (PMID 40607441, 2025). "The contradictory findings highlight the dual role of IL-33 in tumor immunity." (PMID 40539072, 2025). "In addition, activation of innate lymphoid cells group 2 (ILC2) and mast cells by IL-33 facilitates angiogenesis, fibrosis, and extracellular matrix remodelling, features that support tumour progression and metastasis." (PMID 41284319, 2025). "Interestingly, IL-33 remodels the tumor microenvironment by orchestrating the development and maintenance of immune suppressive cells including Tregs, thereby allowing tumor progression." (PMID 40426949, 2025). "In a study on tumor disease, it was also found that IL-33 may activate the ST2-NF-κB signaling pathway, increasing the expression of MMP-2 and MMP-9." (PMID 39172956, 2024). "Considering the pivotal role of PD-1 in cancer immunotherapy and its immunoregulatory functions, we investigated the synergistic effects of IL-33 and anti-PD-1 and found that their combination enhances anti-tumor immunity and improves the efficacy of immunotherapy." (PMID 38430390, 2024). "IL-33 or anti-CSF1R alone could control the tumor volume and tumor weight, whereas the combination of IL-33 and anti-CSF1R showed a further antitumor effect in the subcutaneous MFC-challenged 615-line mouse model." (PMID 38238529, 2024). "Our study provides evidence that specifically the presence of IL33-activated MCs fuels tumor growth and confers pro-tumorigenic activity, suggesting that corresponding patients may benefit from MC depletion." (PMID 38942797, 2024). "The analysis of The Cancer Genome Atlas (TCGA) data and mRNA sequencing from the TCGA revealed that IL-33, expressed in endothelial and epithelial cells, could further contribute to tumor immune responses." (PMID 40236667, 2024).
tumor (continued). "Notably, cisplatin-combined α-IL-33 or α-ST2L treatment groups reduced tumor-infiltrating M2 macrophages and Tregs compared to the cisplatin monotherapy group." (PMID 38778059, 2024). "Similarly, Interleukin 33 (IL-33) is secreted by CAFs during tumor progression but has also been found to enhance HNSCC invasion through MMP2/9 mediated ECM degradation." (PMID 38942893, 2024). "From this, targeting components of the IL‐33‐macrophage‐MMP‐9 axis could represent a potential therapeutic approach toward improving anti‐tumor immune therapy." (PMID 38775220, 2024). "In spontaneous gastric adenoma models, tumor cell-derived IL-33 activates ST2+ mast cells." (PMID 38825642, 2024). "Additionally, IL‐33 can modulate immune cells within the tumour microenvironment, either promoting anti‐tumour immune responses or facilitating tumour cells in evading immune surveillance." (PMID 38923705, 2024). "Statin may also block IL-33 pro-tumor function in immunocompromised settings, which needs to be examined in future research." (PMID 38816352, 2024). "Conversely, other researchers have reported that IL-33 inhibits tumour progression." (PMID 38662248, 2024). "Targeting pathways such as the MCAM-CD163 axis or PDGF-BB/SOX7/IL-33 could reverse this immunosuppression, enhance T-cell infiltration, and disrupt tumor vascular support." (PMID 39796646, 2024). "Stromal cells have also been identified as a primary source of IL-33 among non-immune cells, and IL-33 derived from these cells has been linked to tumor metastasis." (PMID 40236667, 2024). "Additionally, the increased levels of anti-tumor interleukins IL-4, IL-7, IL-28a, and IL-33 in miR-29 overexpressing tumors suggest a role for these microRNAs in bolstering anti-tumor immunity." (PMID 38890285, 2024). "The pleiotropic role of IL-33 in tumor development may depend on the stage of the tumor (early vs. late stages) and IL-33 status (acute vs. chronic release)." (PMID 38778059, 2024). "Blocking IL-33 may influence the cell activation profile and recruitment to the tumour microenvironment." (PMID 38662248, 2024). "In certain scenarios, IL-33 might paradoxically facilitate tumor growth by fostering the expansion of T regulatory cells and myeloid suppressor cells, both known for their pro-tumoral effects on the immune system." (PMID 38881897, 2024). "In our study, mice subjected to IL-33 neutralisation exhibited less tumour growth." (PMID 38662248, 2024). "Moreover, the TGF-β signaling pathway is also involved in an IL-33–TGF-β niche triggered by tumor cells in the TME, affecting erythroid progenitor differentiation." (PMID 39766202, 2024). "In vivo, blocking the OX40L‐OX40 interaction inhibited the anti‐tumor effect of IL‐33." (PMID 38775220, 2024). "In contrast, IL-33 from tumor stroma fosters immune tolerance and suppression via Tregs and MDSCs." (PMID 40236667, 2024). "However, studies have shown that, in some contexts, IL-33 can inhibit the growth of MDSCs and decrease their immunosuppressive capabilities, resulting in enhanced antitumor immune responses and tumor regression." (PMID 40236667, 2024). "Furthermore, T reg depletion or IL-33 treatment enhanced eosinophil infiltration into B16-F10 tumors and reduced tumor growth." (PMID 38254785, 2024). "To evaluate the effect of p38 signaling pathway on tumor progression and macrophage polarization, we established a model of GC abdominal dissemination treated with IL-33 combined with p38 inhibitor (SB203580) and evaluated the anti-tumor efficacy of combined therapy." (PMID 38238529, 2024). "However, another study reported that tumoural expression of IL-33 inhibits tumour growth and modifies the tumour microenvironment, maintaining the controversy about the functional role of IL-33 in cancer." (PMID 38662248, 2024).
tumor (continued). "We next investigated whether treatment of tumour-bearing mice with a neutralising anti-mouse IL-33 antibody (3 μg/mouse delivered once a week) had an impact on tumour growth and the immune compartment." (PMID 38662248, 2024). "In addition, commensal fungi have been observed to colonize pancreatic tumors, stimulating production of IL-33 and suppressing anti-tumor immune responses." (PMID 39172306, 2024). "In addition, IL-33 drives chronic inflammation that supports tumour growth and promotes the activation of regulatory T cells (Tregs) and/or MDSCs." (PMID 38662248, 2024). "The upregulation of somatic stem cell division, elastic fibre assembly, and glycosphingolipid binding in patients with elevated IL33 expression suggests a potential contribution to cancer stemness, extracellular matrix remodelling, and interactions that facilitate tumour progression and metastasis." (PMID 38923705, 2024). "Interleukin-1 receptor-like 1 is the cognate receptor for interleukin-33, an epithelial-derived cytokine which has been reported to confer both pro- and anti-tumorigenic effects, depending on the tumour and cellular context, expression levels, and the nature of the inflammatory environment." (PMID 38301482, 2024). "Activating mast cells and basophils by IL-33 may influence tumor progression by modulating cytokine release and triggering immune complex activation." (PMID 40236667, 2024). "In addition, IL-33 secretion in the tumor sites induces M2-like macrophage differentiation and favors tumor growth and tumor metastasis in esophageal cancer." (PMID 38778059, 2024). "Next, we will review the role of IL-33 in DCs and its potential as a DC-based tumor immunotherapy." (PMID 38825642, 2024). "Conversely, administration of either Malassezia globosa or Alternaria alternata by oral gavage into the tumor-bearing mice had the opposite effect, suggesting that fungi could enhance tumor growth by reshaping the TME through IL-33 signaling." (PMID 39044834, 2024). "Further analysis of tumor cross‐sections with enriched neutrophil infiltrations revealed the upregulation of neutrophil‐related genes such as S100a9, Serpine1, Mt2, Nos2, Mt1, IL33, Adm, and Ero1l." (PMID 39113226, 2024). "We next investigated whether IL-33 blockade modulates the immune compartment in tumour-draining lymph nodes." (PMID 38662248, 2024). "Similarly, IL33 plays a role in tumour immune escape in cancers via Th2 cells and regulatory T cells." (PMID 38398137, 2024). "IL-33 is a danger signal that binds to its receptor ST2L to promote tumor progression." (PMID 38778059, 2024). "It should be noted that although Th2 polarization is generally associated with inhibition of anti-tumor immune responses, it has also been demonstrated that tumoral expression of IL-33 inhibits tumor growth and promotes activity of CD8+ T and NK cells in the TME." (PMID 38612760, 2024). "However, co-administration of IL-33 and PD-1 blockade leads to a significant augmentation in the percentage of ILC2s, particularly iILC2s, and enhances the anti-tumor response." (PMID 38430390, 2024). "IL-33 acts as a potent modulator of the tumor microenvironment, and the authors of the reports now hypothesize that it has either pro- or anti-cancer effects." (PMID 39839625, 2024). "In the realm of human DC-based tumor immunotherapy, IL-33 presents promising avenues." (PMID 38825642, 2024). "Ablation of IL-33 reprograms Tregs to upregulate IFNγ expression and maintain Foxp3 expression, consistent with a “fragile” phenotype, which exhibits reduced suppressive function in vivo, thereby accelerating tumor regression." (PMID 39227959, 2024). "Together, these data suggest that the IL-33/ST2 pathway may be involved in the crosstalk between the tumour and immune cells by modulating the phenotype of head and neck SCC and T cell activity." (PMID 38662248, 2024). "However, it is crucial to recognize that the impact of IL-33 on tumors can be contingent upon the specific tumor microenvironment." (PMID 38881897, 2024).
tumor (continued). "Although IL-33 activated eosinophils released higher quantities of EV, our on chip and transwell experiments with Bodipy FL C16-labelled mouse eosinophils indicate that both Eo5-EV and Eo33-EV were efficiently integrated into target tumor cells." (PMID 39061080, 2024). "Several studies have indicated that antitumor responses caused by tumoral IL-33 overexpression or IL-33 administration do not suppress tumor growth in the absence of cDC1s in Batf3−/− mice." (PMID 38825642, 2024). "The findings indicated that in most cancers, IL33 functions as a tumour‐inhibitor molecule." (PMID 38923705, 2024). "Notably, recombinant IL‐33 therapy by activating myeloid DCs in tumor‐bearing mice restored anti‐tumor T cell activity and increased antigen cross‐presentation within the TME." (PMID 38775220, 2024). "Moreover, it is now clear that IL-33 and cancer cell interactions within the tumour microenvironment regulate cancer stem cell properties and play an important role in tumour progression and metastasis." (PMID 38662248, 2024). "IL-33 is associated with a mouse model of SCC development; therefore, we investigated which cells may be the source of IL-33 in the tumour microenvironment in human SCC lesions." (PMID 38662248, 2024). "In addition to ST2L-expressing macrophages, previous studies have confirmed that IL-33 induces the accumulation of Tregs to promote tumor growth and metastasis." (PMID 38778059, 2024). "Interestingly, the intratumoral fungal mycobiome was identified as the inducer of the increased Il33 in tumor cells." (PMID 38942797, 2024). "Taken together, these data indicate that similarly to mouse eosinophils, activation of human eosinophils with IL-33 stimulates the secretion of EV that induce transcriptional reprogramming in receiving tumor cells towards a block of cell proliferation and of EMT-related markers." (PMID 39061080, 2024). "In our study, anti-IL-33 antibody treatment reduced dysplasia, supporting the hypothesis that the presence of IL-33 in the tumour microenvironment is correlated with faster and more aggressive tumour development in some tumour models." (PMID 38662248, 2024). "In HNSCC, IL-33 has a heterogeneous role among tumours of different sites." (PMID 38662248, 2024). "PPARγ is key in this interaction between ILC2s and cancer cells: it supports the pro-tumoural functions of ILC2s, and this function might be conserved across different IL-33-dependent tumours." (PMID 38662248, 2024). "IL‐33 can act as either an oncogene or a tumor suppressor in different tumor types." (PMID 38737470, 2024). "Likewise, IL-33’s pro-tumor function can play an integral role in tumor promotion by TBK1-IRF3 signaling." (PMID 38816352, 2024). "Furthermore, systemic administration of recombinant IL‐33 can induce an anti‐tumor effect through a CD8+ T cell‐dependent mechanism." (PMID 38775220, 2024). "STC1 may influence CD4+ T cells to secrete cytokines, including IL-17, IL-31, and IL-33, which modulate immune responses via autocrine or paracrine mechanisms, thereby either amplifying or suppressing immune activity within the tumor microenvironment." (PMID 39201771, 2024). "However, when IL-33 is overexpressed in tumor cells or is directly administered, its concentration ranges from tens of ng to several μg14." (PMID 38825642, 2024). "Interestingly, IHC staining demonstrated that the combination of α-IL-33 or α-ST2L with cisplatin reversed cisplatin-induced IL-33 signal in tumor allografts." (PMID 38778059, 2024). "In conclusion, a method for enhancing in vivo immunogenic cDC1s through the direct injection of IL-33 or immunotherapy with IL-33-induced highly immunogenic Mo-DC vaccines may shed light on DC-based tumor immunotherapy." (PMID 38825642, 2024). "Again, we detected increased Il33 expression in AT-ECs of tumor-bearing wild-type mice." (PMID 37749321, 2023).
tumor (continued). "Furthermore, an elevated expression of IL-33 was found in tumor tissues in CRC patients, especially in poor-differentiated CRC cells and in genetically altered intestinal epithelial cells, which drive dysplasia." (PMID 37296602, 2023). "However, several reports have shown that expression of IL33 in the tumor microenvironment correlates with better prognosis and can be associated with activation of NK cells and cytotoxic T cells." (PMID 37848457, 2023). "IL-33 can be secreted by vascular endothelial cells and tumor cells." (PMID 37176567, 2023). "Notably, IL-33 is a pleiotropic cytokine with both pro- and anti-tumor effects, and its rational use in cancer immunotherapy needs to be extensively studied." (PMID 37153553, 2023). "Statistically, it was found that the expression of IL-33 was positively correlated with the tumor stage, tumor size and histological grade of the Asian subgroup in the subgroup analysis of the patient's location, which was consistent with the results of the overall analysis." (PMID 37507682, 2023). "Importantly, whereas endogenous CD44+CD8+ TILs mostly distributed across C4 (canonical TEX) and C2 (effector memory) at the time of tumor regression following PD1d/IL-2v/IL-33 ACT, the C5 TSE effector state identified above was a unique property of OT1 TILs." (PMID 37081150, 2023). "Genetic deletion of IL-33 or anti-fungal treatment resulted in robust PDAC tumor regression." (PMID 38169837, 2023). "In addition, type-2 inflammatory mediator IL33 was only upregulated in KPC-HAPLN1 tumor bearing mice." (PMID 37095087, 2023). "Furthermore, the stimulatory effects of an IL-33-mediated immune response on tumor cell apoptosis far exceeded the inhibitory effect of IL-33 itself on tumor cell apoptosis during 5-FU chemotherapy." (PMID 37056569, 2023). "Furthermore, many studies have shown that treatment with IL-33 or overexpression of IL-33 in tumor cells inhibits tumor progression through boosting type 1 antitumor immune responses in vivo." (PMID 37611111, 2023). "Whether IL-33 directly recruits and/or activates T cells was undetermined, but its positive effect was previously demonstrated in immunogenic tumor models." (PMID 37587450, 2023). "Recent studies have highlighted the controversial role of IL-33 in tumor development 14-16, 20-22." (PMID 37056569, 2023). "However, as the infection course prolongs, the concentration of IL-33 reaches a peak and subsequently decreases, gradually showing a tendency to promote tumor through producing M2 macrophage polarization and increased STAT3 activation." (PMID 37047625, 2023). "The evidence, therefore, indicates that blocking the IL-33/ST2 axis can inhibit tumor development." (PMID 37686309, 2023). "IL33/ IL1RL1 signaling can also promote the accumulation of tumor-infiltrating regulatory T-cells in the TME, suggesting that IL1RL1 may be a novel target for cancer immunotherapy." (PMID 37310469, 2023). "However, the role of IL-33 in cancer therapy remains controversial due to the conflicting effects of IL-33 in tumorigenesis and anti-tumor response." (PMID 37762328, 2023). "Furthermore, tumor-derived IL-33 is able to recruit macrophages into the tumor microenvironment, where they produce prostaglandin E2, which supports stemness." (PMID 37296602, 2023). "The role of IL-33 in neoplasia has been poorly investigated." (PMID 37296602, 2023). "Our findings suggest that recombinant IL-33 or an IL-33-mediated DC vaccine could be an attractive protocol for better tumor immunotherapy." (PMID 37246159, 2023). "In addition, we also discussed the relationship between IL-33 serum expression and major clinicopathological parameters, including tumor stage, lymphatic invasion, vascular invasion, and tumor size." (PMID 37507682, 2023). "Their anti-tumor mechanism has been shown in pancreatic cancer and melanoma models that infiltrating and activating ILC2s by IL-33 could further recruit and activate dendritic cells and T cells." (PMID 37047625, 2023).